HMGA1 (high mobility group AT-hook 1)
Diseases named in the same sentence as HMGA1 in open-access papers (continued):
Sharing a sentence is not in itself a finding about the gene and the disease.
cancer (continued). "HMGA1 is strongly methylated and upregulated in almost all cancer types." (PMID 35864955, 2022). "However, the amount of HMGA1 protein in cancer tissue was correlated with the amount of FOXM1 and G6PD." (PMID 35805937, 2022). "HMGA1 itself can also promote the reprogramming of somatic cells to multifunctional stem cells, which will be useful for regenerative medicine and the treatment of poorly differentiated cancer." (PMID 35864955, 2022). "These elevated mRNA expression levels were associated with an increase in HMGA1 protein levels compared to non-cancerous tissue in the investigated cancer types." (PMID 35805937, 2022). "Other studies have shown that SLC2A3 was directly related to SOX9, TRIM66, and HMGA1, which could promote cancer cell proliferation, migration, and invasion." (PMID 36247875, 2022). "The present study used big data to screen for HMGA1 expression levels in various types of cancers." (PMID 35805937, 2022). "However, the amount of HMGA1 protein in cancer tissue correlated with the amount of FOXM1 and G6PD, with which HMGA1 forms a common pathway for transcriptional regulation and which were similarly associated with TNM stage and overall survival." (PMID 35948739, 2022). "The nuclear building protein HMGA1 can phosphorylate the H1 histone, weaken the affinity between histones and DNA, relax chromatin, and finally achieve the purpose of changing the nuclear hardness and promote the invasion of cancer cells." (PMID 35864955, 2022). "Considering the carcinogenic properties of HMGA1 and its connection with poor prognosis in many types of cancer, some approaches were previously made to invent an in vitro diagnostic kit to quantitatively determine the amount of HMGA1b in peripheral blood of cancer patients." (PMID 35805937, 2022). "HMGA1 has previously been reported to be related to malignant cellular behavior in human cancers." (PMID 36479041, 2022). "High levels of HMGA1 expression lead to poor prognosis in patients with malignant tumors." (PMID 34072941, 2021). "In addition to HMGA1’s function during development, high mobility group proteins are abnormally expressed and localized in virtually every cancer, and their expression levels correlate with the degree of malignancy." (PMID 33526059, 2021). "HMGA1, known to be oncogenic in other cancer types, was found to be upregulated in tumor MF." (PMID 34831413, 2021). "The HMGA1 protein is also found overexpressed in numerous aggressive human cancers." (PMID 35049679, 2021). "Together, these findings implicate RAGE in cancer and suggest that an HMGA1-RAGE autocrine loop could contribute to tumor progression." (PMID 34572547, 2021). "Studies have shown that the silence of HMGA1 represses cancer development." (PMID 33407473, 2021). "We will also discuss how the interplay between the nuclear and extracellular functions of HMGA1 could impact cancer biology and possibly normal development." (PMID 34572547, 2021). "Pan-cancer analysis revealed that HMGA1 was upregulated in various cancer types including CCA." (PMID 34716319, 2021). "Besides, HMGA1 is modulated through its post-translational protein modifications such as methylation, acetylation and phosphorylation in cancer." (PMID 34167089, 2021). "Notably, previous studies demonstrated that HMGA1 knockdown increased autophagosome formation by constraining the activity of the mTOR pathway in cancer cells." (PMID 33536877, 2020). "Indeed, a large amount of evidence has demonstrated the pivotal role of HMGA1 in diverse, aggressive cancers and normal development." (PMID 33536877, 2020). "If so, this interaction could represent a novel clinical intervention point in HMGA1-driven cancers." (PMID 33505435, 2020).
cancer (continued). "In cervical cancer, HMGA1 accelerated the G1/S phase transition by upregulating the expression of Cyclin D1 and Cyclin E1, as demonstrated by in vitro and in vivo experiments in which cancer cells were subcutaneously injected into nude mice." (PMID 31963852, 2020). "HMGA1 is reported to have critical roles in the tumorigenesis and progression of various cancers." (PMID 32477928, 2020). "HMGA1 is known to interact with large transcriptional networks in order to drive cancers." (PMID 33505435, 2020). "The high mobility group A1 (HMGA1) gene plays an important role in numerous malignant cancers." (PMID 30614613, 2019). "Our recent study provided evidence that HMGA1 also has an intrinsic replication fork protection function which could be a contributing factor to the observed chemosensitivity of cancer cells." (PMID 31067275, 2019). "In this paper, we review cancers classified by location and consider whether HMGA1 serves as a biomarker of clinical prognosis." (PMID 30614613, 2019). "In the following section, we had focused on the most intriguing results of our work and how they could provide new opportunities to understand the role of HMGA1 in cancer biology." (PMID 31779212, 2019). "HMGA1 protein was involved in regulation of DNA replication, integration of retroviruses into chromosomes, gene transcription, and metastatic progression of cancer cells." (PMID 31442208, 2019). "The expression of HMGA1 is upregulate in malignant tumor derived from the prostate, breast." (PMID 31196036, 2019). "In all of the literature, HMGA1 is an oncogene in numerous cancers." (PMID 30614613, 2019). "High expression levels of HMGA1 were reported in a variety of human cancers." (PMID 31196036, 2019). "In the following review, we summarize the particular role of HMGA1 in each cancer type." (PMID 30614613, 2019). "HMGA1 as a key regulator of the autophagic pathway in cancer cells could contribute to cancer progression." (PMID 31196036, 2019). "In a step closer to HMGA1, we found that the subcellular localization of S100 proteins could inform cancer outcomes." (PMID 31779212, 2019). "Hmga1 and Hmga2 overlap in their expression in both human and murine PDAC, however knockdown of Hmga1 in Hmga2-deficient cancer cells also did not decrease metastatic ability." (PMID 30228296, 2018). "Because HMGA1 is a hub for regulation of many oncogenes, its overexpression in cancer plays a central role in cancer progression and therefore HMGA1 is gaining increasing attention as a target for development of therapeutic approaches to suppress either its expression or action in cancer cells." (PMID 29462157, 2018). "HMGA1 is a DNA binding protein commonly overexpressed in human cancers." (PMID 29880060, 2018). "Therefore, further studies are needed to clarify the prognostic role of HMGA1 in different types of cancers." (PMID 29416690, 2018). "Thus our data raise a possibility that HMGA1 can drive pluripotency and cancer in part by modulating chromatin accessibility." (PMID 29743479, 2018). "To investigate if Hmga1 could functionally compensate for Hmga2, we stably knocked down Hmga1 in a cancer cell line generated from a KP172CT;Hmga2CK/CK lymph node metastasis." (PMID 30228296, 2018). "Vice versa, overexpression of HMGA1 is found in a wide range of human cancers, including prostate, thyroid, colon, breast, lung, bladder, pancreas, stomach, kidney, uterus, and hepatocellular carcinomas, as well as non-melanoma skin cancers, and hematopoietic malignancies." (PMID 30034366, 2018). "The ability of HMGA1 to regulate the plasminogen activator system may constitute an important mechanism by which HMGA1 promotes cancer progression." (PMID 28924209, 2017). "Therefore, the results presented here envisage the possibility of an innovative cancer therapy based on the suppression of HMGA1 pseudogenes expression and/or the overexpression of miRNAs involved in their ceRNA pathways." (PMID 29149041, 2017).
cancer (continued). "HMGA1 upregulates cellular proliferation and invasion in multiple cancers." (PMID 28404905, 2017). "The dual role for Hmga1 in normal development and poorly differentiated cancers suggests that it regulates cell fate decisions, although a detailed understanding of molecular mechanisms involved in these processes was previously unknown." (PMID 28452345, 2017). "HMGA1 non-coding pseudogenes (HMGA1Ps), HMGA1P6 and HMGA1P7, are two processed pseudogenes that show conserved seed matches for miRNAs targeting the HMGA1 gene and other cancer-associated genes." (PMID 29149041, 2017). "Further, HMGA1 silencing promoted cancer cell chemo sensitivity." (PMID 27602961, 2016). "Information available in this area will aid not only in understanding how cancer cells may escape HMGA1 or CXCR4 targeted therapies but will also provide a rationale for combinatorial therapies targeting both HMGA1 and CXCR4." (PMID 27602961, 2016). "Therefore, high HMGA1 gene or its pseudogene expression allows to increase other oncogene protein levels then contributing to cancer progression." (PMID 26895108, 2016). "Expression levels of HMGA1 varied among the cancer cell lines." (PMID 27602961, 2016). "However, the correlation between S100A13 and HMGA1 during cancer progression is not yet well understood." (PMID 27008379, 2016). "We demonstrated that these proteins lie downstream of HMGA1 (both in a cellular model and in clinical specimens) and are involved in the modulation of cell motility, which is one of the first characteristics a cancer cell must acquire to disseminate." (PMID 26527623, 2016). "Moreover, the induced overexpression of HMGA1 in immune-inactivated nude mice leads to malignant tumor formation and HMGA1 expression also correlates with the metastatic potential of the tumor, making HMGA1 a key player during cancerogenesis." (PMID 26117853, 2015). "D Angelo D49 reported that the blockage of HMGA1 expression was a promising approach to enhance cancer cell chemosensitivity, which supported HMGA1 could increase the sensitivity of cancer cells to antineoplastic drugs." (PMID 25818003, 2015). "In addition, tumorigenic properties such as cell mobility, invasion and anchorage-independent cell growth were diminished, making the HMGA1 knockdown a promising approach for fighting HMGA1-dependent cancer formation." (PMID 26117853, 2015). "Thus, targeting HMGA1 is increasingly gaining attention in the field of anti-cancer therapeutical approaches." (PMID 26117853, 2015). "In conclusion, the results presented herein indicate that HMGA1 has a specific role in making decisions about stem cell fate, and thus, targeting HMGA1 may represent a promising CSC-specific anti-cancer strategy." (PMID 24833610, 2014). "In conclusion, our finding that HMGA1P7-overexpressing MEFs grow faster and senesce later than their WT counterpart sustains our model in which HMGA1Ps act as ceRNAs that regulate HMGA1 and other genes by competing for shared miRNAs thus contributing to cancer progression." (PMID 25268743, 2014). "We asked whether HMGA1 pseudogenes affect HMGA1 protein levels, and, consequently, whether they play a critical role in cancer progression." (PMID 25268743, 2014). "Together, these findings suggest that HMGA1 could function in tumor progression by reprogramming differentiated cells into poorly differentiated, stem-like cancer cells." (PMID 23658826, 2013). "In addition, knock-down of HMGA1 depletes cancer initiator/cancer stem cells and prevents tumorigenesis at limiting dilutions." (PMID 23658826, 2013). "Therefore, our results suggest that HMGA1 plays a pivotal role in orchestrating a molecular network that sustains the invasiveness of cancer cells." (PMID 23945276, 2013). "Further studies are now needed to develop approaches to target HMGA1 in cancer." (PMID 23658826, 2013). "TFPD1, E2F6, IRF1, and HMGA1 are upregulated in all cancer samples." (PMID 24564251, 2013).
cancer (continued). "Together, these studies and our findings presented here suggest that strategies to induce expression of HMGA1 and that of other pluripotent genes could reprogram malignant tumors into cells that respond to differentiating agents." (PMID 23166588, 2012). "Together, these studies in cancer and pluripotent stem cells suggest that HMGA1 could function to reprogram cells to a more primitive, undifferentiated, stem-like state." (PMID 23166588, 2012). "Because HMGA1 is enriched in embryonic stem cells, tissue-specific stem cells, and virtually all aggressive tumors studied to date, our findings are likely to relevant not only to diverse human cancers, but also to normal development." (PMID 22276142, 2012). "The high mobility group A1 (HMGA1) gene is highly expressed during embryogenesis and enriched in hESCs, hematopoietic stem cells (HSCs), and poorly differentiated or refractory cancers, with low or undetectable expression in adult, differentiated tissues." (PMID 23166588, 2012). "Recent studies identified HMGA1 as a key transcription factor enriched in human embryonic stem (ES) cells, hematopoietic stem cells, refractory leukemia and high-grade/poorly differentiated cancers from the breast, brain, and bladder." (PMID 22276142, 2012). "Although further studies are needed, these HMGA1 pathways could be exploited in regenerative medicine or as novel therapeutic targets for poorly differentiated, stem-like cancers." (PMID 23166588, 2012). "HMGA1 proteins were first linked to cancer over 25 years ago when they were discovered as abundant, nonhistone chromatin binding proteins in human HeLa cervical cancer cells." (PMID 22053823, 2011). "Hence, studies to identify the HMGA1 transcriptome during tumorigenesis should have important implications, not only for cancer, but also for development and the stem cell phenotype." (PMID 22053823, 2011). "HMGA1, an architectural transcription factor that plays a crucial role in tumorigenesis, chemotherapy resistance and cancer stem cell transformation in many human cancers, is intrinsically disordered and cannot be targeted by conventional small molecule drug therapy." (PMID 41183073, 2025). "This revealed that HMGA1 consistently activates a core set of pathways essential for rapid cell proliferation, including the cell cycle, DNA replication, pyrimidine metabolism, spliceosome, and proteasome, which were enriched in cancers such as BRCA, COAD, and LIHC." (PMID 41463532, 2025). "Generation of these two new engineered adenovirus vectors was based on the hypothesis that suppression of HMGA1 synthesis in cancer cells would potentially provide stronger anti-cancer activity compared to infection with adenoviral vectors exhibiting HMGA1 sequestration capability alone." (PMID 41183073, 2025). "In summary, our results provide a further understanding of HMGA1 in cooperation with FOXM1 within the nucleus to regulate gene transcription in controlling G2/M cell cycle progression, which could provide a potential cancer treatment strategy by targeting both HMGA1 and FOXM1 in cancers." (PMID 37240870, 2023). "the HMGA1 gene may be a potential candidate for DNA methylation targeting anti-cancer therapy." (PMID 35805937, 2022). "In addition, data suggest that HMGA1 might promote chromatin relaxation through a histone H1-mediated mechanism, impacting nuclear stiffness and thus favouring the invasiveness of cancer cells." (PMID 35504904, 2022). "Notably, HMGA1 is also reported to be an oncogene in diverse cancer types." (PMID 35785026, 2022). "Indeed, crosstalk between nuclear and secreted HMGA1 could change our understanding of tumor development and reveal novel therapeutic opportunities relevant to diverse human cancers overexpressing HMGA1." (PMID 34572547, 2021). "In addition, as a key regulator of the autophagic pathway in cancer cells, HMGA1 might contribute to cancer progression." (PMID 32477928, 2020).
cancer (continued). "In addition, a better grasp of the roles of Hmga1 in healthy development could help to appreciate how it participates in a range of adult cancers." (PMID 32965216, 2020). "Thus, the early expression of Hmga1 in neural crest precursors, together with its reported role in maintaining stemness and self-renewal properties in various stem cell and cancer systems, may indicate a role in maintaining neural crest stemness." (PMID 32965216, 2020). "Therefore, it is interesting to note that Hmga1 may play parallel roles in neural crest development and cancer metastasis." (PMID 32965216, 2020). "However, little is known about how HMGA1 governs these cancer-related gene networks." (PMID 31311575, 2019). "However, the prognostic role of HMGA1 in different types of cancers remains controversial." (PMID 29416690, 2018). "It was reported that HMGA1 overexpression could promote the growth and invasion of cancer cells." (PMID 27008379, 2016). "Besides cancers, pseudogenes also involve in the development of other diseases, such as HMGA1-p." (PMID 25502083, 2015). "Therefore, the decreased ATM levels in the presence of HMGA1 overexpression might increase pro-survival Akt signaling after treatment of the cancer cells with the antineoplastic drugs." (PMID 25409711, 2014). "Therefore, our data indicate a critical role for HMGA1 in regulating both self-renewal and the symmetric/asymmetric division ratio in CSCs, suggesting that blocking HMGA1 function may be an effective anti-cancer therapy." (PMID 24833610, 2014). "Our findings suggest that the blockage of HMGA1 expression is a promising approach to enhance cancer cell chemosensitivity, since it could increase the sensitivity of cancer cells to antineoplastic drugs by inhibiting the survival signal and DNA damage repair pathways." (PMID 25409711, 2014). "Interestingly, a recent study has shown that human HMGA1 promoter is target of E2F1 and the deregulated RB1/E2F1 pathway might contribute to deregulation of HMGA1 in cancer." (PMID 25364713, 2014). "Therefore, the targeted suppression or inactivation of HMGA1 could be a potential therapeutic strategy with which to increase chemosensitivity in cancer cells." (PMID 25409711, 2014). "Consequently, it appears that HMGA1P6 and HMGA1P7 expression may contribute to cancer progression by acting as decoys for cancer-related genes other than HMGA1." (PMID 25268743, 2014). "Thus, given our observations that HMGA1 is involved in the MET, we asked whether HMGA1 influences the cancer stem cell population and its self-renewal capacity." (PMID 23945276, 2013). "Because silencing HMGA1 has profound effects on oncogenic properties in vitro, primary tumorigenesis and metastatic progression in vivo, and expression of genes involved in epithelial-mesenchymal transition, we sought to determine its role in cancer stem cell characteristics." (PMID 23658826, 2013). "Because HMGA1 may not only serve as a prognostic marker but may also be causally involved in metastatic progression, and because HMGA1 is not present in most adult normal tissues, it may become an attractive target for cancer therapy." (PMID 23935884, 2013). "On the one hand, the interesting gene list contains many cancer genes, such as ERBB2, HMGA1, and MET, that are related to these cancer types, which have been widely studied." (PMID 40139908, 2025). "Elevated HMGA1 levels correlated with reduced overall survival (OS) in GBMLGG, LUAD, LIHC, KIRP, PAAD, and additional cancers." (PMID 41463532, 2025). "To define the oncogenic pathways driven by HMGA1, we performed Gene Set Enrichment Analysis (GSEA) across eight cancer types." (PMID 41463532, 2025). "Previous research has demonstrated that hsa-miR-765 regulates cancer progression by modulating the ERK/Akt/AMPK signaling pathway and the expression of HMGA1 protein." (PMID 40076502, 2025).